HIGD1A (HIG1 hypoxia inducible domain family member 1A)
Description:
Proposed subunit of cytochrome c oxidase (COX, complex IV), which is the terminal component of the mitochondrial respiratory chain that catalyzes the reduction of oxygen to water. May play a role in the assembly of respiratory supercomplexes.
Synonyms: RCF1a; HIG1; DKFZP564K247
Tractability: Antibody: UniProt predicts a signal peptide or a membrane-spanning region. PROTAC: ubiquitination databases record sites on it; its protein half-life has been measured.
Gene: Protein-coding gene on chromosome 3 (42,782,908 to 42,804,527, reverse strand). Ensembl gene ENSG00000181061.
Subcellular location: Mitochondrion membrane; Mitochondrion inner membrane
Subcellular location (Human Protein Atlas): Mitochondria; Nucleoplasm
Pathways (Reactome):
Cellular responses to stimuli: Regulation of gene expression by Hypoxia-inducible Factor
Metabolism: Complex IV assembly
Gene Ontology:
Biological process: negative regulation of apoptotic process; mitochondrial respirasome assembly
Cellular component: mitochondrion; protein-containing complex; mitochondrial inner membrane; membrane; mitochondrial membrane; nucleus
Genetic constraint (gnomAD): Loss-of-function variants: 7 observed, 9.06 expected, observed/expected ratio (o/e) 0.77, 90% interval 0.44 to 1.44. That is too few expected variants to judge how well the gene tolerates losing a copy. Missense variants: 85 observed, 98.15 expected, observed/expected ratio (o/e) 0.87, 90% interval 0.73 to 1.04. Synonymous variants: 30 observed, 33.49 expected, observed/expected ratio (o/e) 0.9, 90% interval 0.67 to 1.22.
Homologues: Orthologues: pig HIGD1A (92% identical), guinea pig HIGD1A (87% identical), mouse Higd1a (86% identical), rat Higd1a (85% identical), rat Higd1al1 (80% identical), tropical clawed frog higd1a (72% identical), zebrafish higd1a (66% identical), Drosophila melanogaster CG11825 (45% identical). Paralogues in human: HIGD1C (60% identical), HIGD1B (46% identical), HIGD2A (34% identical), HIGD2B (32% identical).
Diseases named in the same sentence as HIGD1A in open-access papers:
HIGD1A is named in the same sentence as 34 diseases in open-access papers, as found by Europe PMC text mining. Sharing a sentence is not in itself a finding about the gene and the disease. The quoted sentences say what the papers report.
glioma (5 papers, 2020 to 2024). A benign or malignant brain and spinal cord tumor that arises from glial cells (astrocytes, oligodendrocytes, ependymal cells). "In glioma cells, residual HIGD1A levels are maintained separately from HIF induction, and linked to the activity of the DNA methyl transferase-1 (DNMT1) on HIGD1A HREs." (PMID 37686461, 2023). "The knockdown of LEF1-AS1 represses cell proliferation and suppressed tumor growth while activating apoptosis in glioma via the downregulated LEF1-AS1/miR-489-3p/HIGD1A axis." (PMID 37114036, 2023). "Then, we examined the function of HIGD1A in glioma cells after validating the declined HIGD1A expression by sh-HIGD1A." (PMID 32826866, 2020). "In rescue assays, upregulation of HIGD1A remedied the inhibitory impacts of LEF1-AS1 silence on glioma cell growth." (PMID 32826866, 2020). "It was revealed that HIGD1A depletion inhibited the proliferation and promoted the apoptosis of glioma cells." (PMID 32826866, 2020). "In general, LEF1-AS1 facilitated glioma cell proliferation and inhibited cell apoptosis through function as a ceRNA to target miR-489-3p and thereby upregulated HIGD1A expression." (PMID 32826866, 2020). "The expression of HIGD1A was tested in glioma cell lines (U251, T98MG, SWO38, and U373MG) and control cell lines (HEB and NHA)." (PMID 32826866, 2020). "In addition, HIGD1A was found to be upregulated in glioma cells and the knockout of HIGD1A led to decreased cell proliferation and increased apoptosis in glioma." (PMID 38395945, 2024). "HIGD1A has been proven to be a meaningful biomarker in pancreatic cancer and glioma." (PMID 39108265, 2024). "Besides, the regulatory mechanism of ceRNA network consisting of LEF1-AS1, miR-498-3p and HIGD1A was elucidated in glioma." (PMID 32826866, 2020). "Depletion of HIGD1A led to decreased cell proliferation and activated apoptosis in glioma." (PMID 32826866, 2020). "Rescue assays were constructed to validate whether HIGD1A affected the modulatory effects of LEF1-AS1 on glioma cellular processes." (PMID 32826866, 2020). "Further, HIGD1A identified as the target gene of miR-489-3p was upregulated in glioma cells." (PMID 32826866, 2020). "In summary, our studies corroborated the regulatory mechanism of LEF1-AS1/miR-489-3p/HIGD1A axis in glioma, suggesting that targeting LEF1-AS1 might be a promising method for glioma therapy in the future." (PMID 32826866, 2020). "Results indicated that HIGD1A was highly expressed in glioma cell lines." (PMID 32826866, 2020). "Additionally, LEF1-AS1 knockdown-mediated function in the behaviors of glioma cells was offset by overexpressing HIGD1A." (PMID 32826866, 2020). "In addition, HIGD1A was tested to be significantly upregulated in glioma cells." (PMID 32826866, 2020). "Therefore, whether LEF1-AS1 could regulate HIGD1A via miR-498-3p to affect glioma development was worthy exploring." (PMID 32826866, 2020). "In terms of glioma cell apoptosis, the accelerating effects of LEF1-AS1 depletion on apoptosis was neutralized by augmented HIGD1A, suggested by flow cytometry analysis and TUNEL assay." (PMID 32826866, 2020).
colon adenocarcinoma (4 papers, 2021 to 2024). "Interestingly, HIGD1A might play different roles in multiple types of cancer, such as tumor-promoting role in pancreatic cancer and tumor-suppressing function in colon adenocarcinoma." (PMID 38395945, 2024).
pancreatic cancer (4 papers, 2024 to 2025). "Based on these results, we presumed that SASP may not be the main cause of HIGD1A‐knockdown‐induced cellular senescence, which is consistent with the results reported in pancreatic cancer cell lines." (PMID 40801481, 2025). "However, HIGD1A knockdown in pancreatic cancer cells did not affect cell apoptosis instead of causing cell cycle retardation through induction of p27KIP1 and RB hypo-phosphorylation." (PMID 38395945, 2024).
ischemic heart disease (2 papers, 2013 to 2024). "Specifically, we show that in the setting of ischemic heart disease, hypoxic-ischemic encephalopathy and cancer, nuclear localization of HIGD1A correlates with severity of stress." (PMID 23646141, 2013).
liver cancer (2 papers, 2023 to 2024). An epithelial or non-epithelial malignant neoplasm that arises from the liver. "Moreover, it implies a promising target for HCC therapeutic intervention, suggesting that the development of HIGD1A inhibitors could be potentially used for the treatment of liver cancer." (PMID 38395945, 2024). "However, in our study, the expression of HIGD1A in HCC was comparable to or even slightly lower than that detected in normal tissue samples obtained from public datasets, although HIGD2A expression was markedly elevated in patients with liver cancer." (PMID 37041638, 2023).
adenoma (1 paper, 2021). A neoplasm arising from the epithelium. "The expression of HIGD1A exhibited a significant reduction in two subtypes of adenoma and six subtypes of CRC, while the down-regulation of SUCLG2 and SLC25A24 showed more advantages in rectal mucinous adenocarcinoma." (PMID 34174878, 2021). "Furthermore, another investigation uncovered that the expression of HIGD1A was significantly reduced in two subtypes of adenoma and six subtypes of CRC, but the difference in rectal mucinous adenocarcinoma was significant only in one analysis." (PMID 34174878, 2021).
colorectal tumors (1 paper, 2021). "Next, to further understand the potentials of HIGD1A, SUCLG2, and SLC25A24 as the IPFs for CRC, we investigated their mRNA expression in unique datasets of CRC and different subtypes of colorectal tumors through the Oncomine database." (PMID 34174878, 2021).
female infertility (1 paper, 2025). Diminished or absent ability of a female to achieve conception. "By systematically studying the role of HIGD1A in regulating granulosa cell and ovarian functions as well as its corresponding mechanisms, a novel regulatory mechanism underlying OS‐related female infertility is revealed, and provided a potential molecular target for anti‐OS therapies." (PMID 40801481, 2025).
glioblastoma (1 paper, 2013). The most malignant astrocytic tumor (WHO grade IV). "To assess the relevance of nuclear HIGD1A location in antiangiogenesis therapy, we first examined HIGD1A expression in glioblastoma xenografts before and after administration of Bevacizumab (Avastin)." (PMID 23646141, 2013). "Therefore, to determine if HIGD1A was similarly induced in human glioblastomas following anti-angiogenesis treatment in vivo, we examined HIGD1A expression in human glioblastoma biopsies obtained before and after administration of Bevacizumab (Avastin) to patients." (PMID 23646141, 2013).
Hepatic steatosis (1 paper, 2019). Steatosis is a term used to denote lipid accumulation within hepatocytes. "Mice fed a HFD developed a fatty liver, and hepatic steatosis was more severe in mice injected with adenovirus expressing Higd1a shRNA." (PMID 31089410, 2019).
hypoxic-ischemic encephalopathy (1 paper, 2013). "Additionally, we demonstrate that nuclear HIGD1A is a potential marker of metabolic stress in vivo, frequently observed in diverse pathological states such as myocardial infarction, hypoxic-ischemic encephalopathy (HIE), and different types of cancer." (PMID 23646141, 2013).
lymphoma (1 paper, 2013). A malignant (clonal) proliferation of B- lymphocytes or T- lymphocytes which involves the lymph nodes, bone marrow and/or extranodal sites. "Based on the gene expression studies, we identified BAT3/BAG6, HIGD1A, and FAT10/UBD as immunohistochemical markers expressed in the tumor cells of all three lymphomas." (PMID 24244368, 2013).
melanoma (1 paper, 2013). A malignant, usually aggressive tumor composed of atypical, neoplastic melanocytes. "Other examples include HIGD1A and PAICS (both found in the melanoma library)." (PMID 23717670, 2013).
non-alcoholic fatty liver disease (1 paper, 2025). "In addition, HIGD1A has been associated with various diseases such as cancer, non-alcoholic fatty liver disease, type II diabetes, and mitochondrial diseases; however, studies directly linking HIGD1A to LSS remain limited." (PMID 39857775, 2025).
ovarian diseases (1 paper, 2025). "Based on these preliminary observations, we are aim to further explore the potential role of the HIF‐1α/HIGD1A axis in the pathogenesis of hypoxia‐related ovarian diseases, such as ovarian torsion and ovarian tissue transplantation." (PMID 40801481, 2025).
proteinopathy (1 paper, 2020). "Thus, Myr could possibly enhance SNX14 to induce autophagy and lipid consumption, and it may upregulate HIGD1a to reduce the oxidative stress caused by proteinopathy and lipid accrual in infected CF cells." (PMID 32781626, 2020).
psoriasis (1 paper, 2025). An autoimmune condition characterized by red, well-delineated plaques with silvery scales that are usually on the extensor surfaces and scalp. "We identified 34 housekeeping genes associated with psoriasis and observed that the co-expression relationships between six genes (APOL2, DCUN1D3, UBE2F, HIGD1A, PPIF, and STAT3) and known psoriasis-related genes differed significantly between diseased and healthy individuals." (PMID 40959079, 2025).
rectal mucinous adenocarcinoma (1 paper, 2021). "This suggested that SUCLG2 and SLC25A24 might be used as helper genes for HIGD1A in clinical diagnosis, which might improve the diagnostic accuracy of rectal mucinous adenocarcinoma." (PMID 34174878, 2021).
tumor (12 papers, 2013 to 2024). "HIGD1A expression was detected more frequently and stronger in tumor cells of different variants of NLPHL (6/10, 8/10 and 9/10 cases, respectively in the patterns A, C and E) than in THRLBCL (4/10 cases)." (PMID 24244368, 2013). "When we integrated several of these genes into a multivariate LASSO regression model to define poor tumour outcome in the BX‐Neu+ mouse cohort, four genes were identified that were associated with poor survival in BX‐Neu+ mice: Oip5, Higd1a, Shc4 and Scrg1." (PMID 38344872, 2024). "TRAP1 and P4HA1 are highly expressed at the intracellular level, whereas PPARGC1A, EFHD1, and HIGD1A are only expressed by a minority of tumor cells." (PMID 37903487, 2024). "Hypoxia-inducible gene domain protein-1a (HIGD1A) is typically induced via epigenetic regulation and promotes tumor cell survival during hypoxia." (PMID 38395945, 2024). "Perinecrotic tumor areas demonstrated nuclear HIGD1A localization, whereas distal regions to necrotic cores contained predominantly extranuclear HIGD1A." (PMID 23646141, 2013). "Moreover, there was a statistically significant decline in the average methylation level within the promoter region of HIGD1A with increasing tumor grade." (PMID 38395945, 2024). "In addition, by controlling AMPK activity and cellular reactive oxygen species (ROS) levels in the body, HIGD1A can lessen tumor cell death and contribute to the development and spread of malignancy." (PMID 39108265, 2024). "HIGD1A weakens oxidative stress during hypoxia and glucose deficiency by activating the AMPK pathway, inhibiting mitochondrial respiration, reducing ROS generation, and mediating cell dormancy, alleviating tumor cell death." (PMID 39108265, 2024). "Finally, we investigated the impact of HIGD1A on HCC tumor growth using subcutaneous and intrahepatic orthotopic xenograft tumor models established with three different HCC cell lines." (PMID 38395945, 2024). "HIGD1A may play an important role in tumor dormancy or recurrence mechanisms during tumor cell adaptation to extreme environments." (PMID 33552987, 2020). "HIGD1A, EFHD1, and PPARGC1A were found to be overexpressed in normal tissue, whereas TRAP1 and P4HA1 were found to be overexpressed in CRC tumor tissue (p < .001)." (PMID 37903487, 2024). "Consistent with the in vitro findings, the expression of Ki67 was markedly reduced in the HIGD1A knockdown groups of different HCC cell lines, indicating a suppressed tumor proliferation." (PMID 38395945, 2024). "During glucose deprivation, HIGD1A regulates oxygen consumption, ROS production, and AMPK activity to modulate cell survival and tumor growth." (PMID 29507648, 2018). "First, HIGD1A expression was examined within a cohort of paired tumor tissues and adjacent non-tumor liver tissues from 24 HCC patients." (PMID 38395945, 2024). "Furthermore, the PFS analyses revealed that the decreased expression of HIGD1A and SLC25A24 accelerated the tumor malignancy." (PMID 34174878, 2021). "Consequently, HIGD1A, SUCLG2, and SLC25A24 were all down-regulated in CRC and exhibited a stably declined expression throughout the tumor progression." (PMID 34174878, 2021). "Regions distal to tumor necrotic areas stained weakly for CA9 and HIGD1A." (PMID 23646141, 2013). "Moreover, HIGD1A knockdown in HCC cells arrested the cell cycle at the G2/M phase and promoted hypoxia-induced cell apoptosis, resulting in great inhibition of cell proliferation, migration, and invasion, as well as tumor xenograft formation." (PMID 38395945, 2024). "Hypoxia‐inducible gene domain family member 1A (HIGD1A) is a HIF‐1α The regulated mitochondrial proteins can regulate oxygen consumption and reactive oxygen species production under hypoxic conditions, thereby activating the dormancy mechanism of tumor cells and enabling their survival." (PMID 37903487, 2024).
tumor (continued). "The results demonstrated that the knockdown of HIGD1A significantly influenced tumor growth across all three HCC cell lines, with a significant reduction in both volume and weight of subcutaneous tumors and orthotopic tumors in the HIGD1A knockdown groups compared to the control group." (PMID 38395945, 2024). "In the comparison of LP cells of typical NLPHL with tumor cells of THRLBCL, the highest number of differentially expressed genes was observed; 16 genes were upregulated more than 1.7-fold in the LP cells of typical NLPHL, including HIGD1A (upregulated 2.0-fold)." (PMID 24244368, 2013).
cancer (11 papers, 2013 to 2025). A tumor composed of atypical neoplastic, often pleomorphic cells that invade other tissues. "To elucidate the underlying mechanism of HIGD1A regulation on HCC cancer phenotype, we conducted an RNA-seq analysis on HepG2 cells that had been infected with shCtrl and shHIGD1A." (PMID 38395945, 2024). "The expression of TRAP1 in pan‐cancer was shown to be substantially inversely linked with that of HIGD1A and EFHD1, and positively correlated with that of PPARGC1A, according to a correlation study of 5 MRGs." (PMID 37903487, 2024). "HIGD1A is up-regulated in a variety of human cancers and has been implicated as an oncogene because it promotes cell proliferation and survival." (PMID 37041638, 2023). "In this study, we examined HIGD1A expression in HCC tissues and cell lines and explored the effect and mechanism of HIGD1A on the cancer phenotype and metabolism of HCC through in vitro and in vivo experiments." (PMID 38395945, 2024). "HIGD1A has a dual effect of promoting and inhibiting cancer and is regarded as HIF-1α’s target genes." (PMID 39108265, 2024). "The promoter of the HIGD1A gene is differentially methylated in human cancers, preventing its hypoxic induction." (PMID 29507648, 2018). "HIG1 domain family member 1A (Higd-1a) interacts with dynamin-like 120 kDa protein to maintain the morphological and functional integrity of the mitochondria and thus plays an important role in the progression of malignant tumors." (PMID 34787061, 2021). "Additionally, HIGD1A methylation levels were positively correlated with individual cancer stages." (PMID 38395945, 2024). "During glucose starvation, HIGD1A reduced mitochondrial respiration, reactive oxygen species (ROS) production, and AMP-dependent protein kinase (AMPK) activity to promote cancer cell survival." (PMID 38395945, 2024). "As such, expression of both mammalian HIGD1A and HIGD2A is induced under hypoxia, and mammalian HIGD1A regulates oxygen consumption, production of reactive oxygen species (ROS), and AMPK (5′ adenosine monophosphate-activated protein kinase) activity during glucose deprivation in cancer cells." (PMID 33291261, 2020).
mitochondrial disease (2 papers, 2020 to 2025). "Similarly, the expression of HIGD1A in different cellular and animal models of mitochondrial disease was shown to attenuate their deleterious phenotypes by increasing CIV activity and ATP production while decreasing ROS levels." (PMID 33291261, 2020).
HIGD1A also shares sentences with these, for which no sentence is quoted: breast carcinoma (2 papers); Cerebral ischemia (2); cecum adenocarcinoma (1); colon cancer (1); colon mucinous adenocarcinoma (1); diabetes (1); hepatocellular carcinoma (1); hypothyroidism (1); lung adenoma (1); myocardial infarction (1); rectal adenocarcinoma (1); rectosigmoid adenocarcinoma (1); type II diabetes (1).